RN7SKP191 (RN7SK pseudogene 191)
Gene: Miscellaneous RNA gene on chromosome 9 (105,096,756 to 105,097,061, forward strand). Ensembl gene ENSG00000201583.
Homologues: Orthologues: chimpanzee 7SK (99% identical), guinea pig 7SK (58% identical). Paralogues in human: RN7SKP71 (76% identical), 7SK (75% identical), RN7SKP255 (74% identical), RN7SKP180 (73% identical), RN7SKP189 (73% identical), RN7SKP257 (73% identical), RN7SKP245 (72% identical), RN7SKP77 (72% identical), RN7SKP79 (72% identical), RN7SKP160 (72% identical), RN7SKP173 (72% identical), RN7SKP269 (72% identical), and 284 more.